BACE1 (beta-secretase 1)
Diseases named in the same sentence as BACE1 in open-access papers (continued):
Sharing a sentence is not in itself a finding about the gene and the disease.
schizophrenia (25 papers, 2008 to 2026). A major psychotic disorder characterized by abnormalities in the perception or expression of reality. "BACE1 cleavage of NRG1 regulates myelination, and increased BACE1 cleavage of NRG1 has been implicated in the development of schizophrenia." (PMID 35119166, 2022). "Pathologically, BACE1 has also been implicated in the development of other diseases, including type 2 diabetes, schizophrenia, and epilepsy." (PMID 35119166, 2022). "While hypo-function of Nrg1 is linked to schizophrenia-like behaviors in BACE1-null mice, enhanced expression of either BACE1-cleaved Nrg1-ntf fragment or of full-length Nrg1 surprisingly also induces schizophrenia-like behaviors." (PMID 28469554, 2017). "Abnormal phenotypes have been reported in BACE1-deficient mice, including a schizophrenia-like phenotype, abnormal muscle spindle formation, and retinal pathology." (PMID 25592972, 2015). "This abrogated cleavage of NRG1, which is genetically linked to schizophrenia, has also been implicated in schizophrenia-like phenotypes described in BACE1-/- mice." (PMID 20731874, 2010). "In this regard, preclinical studies demonstrated that BACE1-deficient mice displayed severe abnormalities including schizophrenia-like behaviors, hypomyelination and early lethality, which suggests that BACE1 inhibitors may exert alarming adverse effects." (PMID 33086751, 2020). "Interestingly, overexpression of secreted Nrg1 by Bace1 cleavage (Nrg1-ntfβ) in mice was sufficient to cause schizophrenia-like phenotypes." (PMID 28993723, 2017). "It will provide new insights into how BACE1-dependent NRG1 proteolytic processing could contribute to the pathophysiology of schizophrenia, and help to discover the underlying biomarker of schizophrenia, which is essential for early diagnosis of the disorder disease and effective medical treatment." (PMID 28993723, 2017). "This is in line with clinical observations that increased Nrg1 or ErbB4 transcripts and proteins are found in schizophrenia patients, supporting the importance of balanced BACE1-cleaved Nrg1 in synaptic functions." (PMID 28469554, 2017). "In this section, we will focus on the function of BACE1-dependent NRG1 cleavage in schizophrenia clinical studies." (PMID 28993723, 2017). "Together, results suggest the possible relationship between BACE1 and dysfunctions of the brain such as schizophrenia, epileptic seizures, and AD." (PMID 28993723, 2017). "Our review will provide a better understanding of Nrg1 in schizophrenia and a potential strategy for using BACE1 cleavage of Nrg1 as a unique biomarker for diagnosis, as well as a new therapeutic target, of schizophrenia." (PMID 28993723, 2017). "In future studies, it will be important to investigate BACE1, Nrg1-related molecular pathways, and neural circuits in endophenotypes resembling features of schizophrenia." (PMID 28993723, 2017). "While changes in Nrg1 expression levels in schizophrenia still remain controversial, understanding the BACE1-cleaved Nrg1-ntf and Nrg1/ErbB4 signaling in schizophrenia neuropathogenesis is essential and important." (PMID 28993723, 2017). "Due to various BACE1 substrates, it is helpful to investigate their role and further illustrate the function of Nrg1 downstream signaling pathways in schizophrenia." (PMID 28993723, 2017). "Although BACE1−/− mice indicate that BACE1 is involved in memory, myelination, seizure, axon guidance, emotions, schizophrenia and vision, the mechanisms of these BACE1 null neurological phenotypes are not fully understood." (PMID 23820808, 2013). "One possible side effect identified in a BACE1 knockout mouse (BACE1-/-) involved NRG1, a substrate for BACE1 and a protein implicated in schizophrenia." (PMID 22654723, 2011). "However, strong inhibition of BACE-1 causes serious adverse effects including sensorimotor gating deficits and schizophrenia, indicating that the balance of BACE-1-mediated signaling appears to be important in AD." (PMID 36232612, 2022).
schizophrenia (continued). "Furthermore, sexual dimorphism was reported in males exhibiting higher BACE1 expression compared to females with schizophrenia and HC individuals." (PMID 33066807, 2020). "Animal studies suggest that BACE1 might be involved in the pathology of schizophrenia via cleaving substrates to stimulate the downstream signal pathway." (PMID 28993723, 2017). "Since most studies have compared the total Nrg1 levels between schizophrenia and healthy controls, it is critical to know whether the specific activity of BACE1 in cleavage of Nrg1 plays an important role in schizophrenia." (PMID 28993723, 2017). "Taken together, there is strong evidence from NRG1 overexpression and knockout studies in mice for the association of altered developmental NRG1-ErbB4 signalling with schizophrenia; however, relatively few studies have addressed the role of BACE1-cleaved NRG1 in the mature brain." (PMID 27456313, 2016). "Indeed, Bace1 knockout mice exhibit severe phenotypes such as schizophrenia-like symptoms, muscle abnormality, retinal pathology, and early lethality." (PMID 25592972, 2015). "BACE1-null mice display complex neurological phenotypes, including growth retardation, memory deficits, hypomyelination, seizures, axon guidance defects, and schizophrenia-like behaviors." (PMID 23820808, 2013). "BACE1 knockout mice are viable and fertile but recent data indicate that these mice could harbor axon hypomyelination, schizophrenia-like and epileptic-like behaviors." (PMID 23039869, 2012). "BACE1-/-mice exhibit endophenotypes typically seen in schizophrenia, leading researchers to test whether partial BACE1 inhibition decreases Aβ load while limiting unwanted side effects." (PMID 22654723, 2011). "However, there are contradictory findings reported in the literature; one study reported elevated cleavage of neuregulin-1 by β-secretase (BACE1) in the plasma of patients with schizophrenia and a relationship between BACE1-cleaved-NRG1 activity and both disease severity and disease duration." (PMID 35337293, 2022). "In schizophrenia, genetic alterations, i.e., in BACE1, could play a key role." (PMID 34679416, 2021). "Decreased spine density in hippocampal pyramidal neurons was also observed in Bace1-/- mice via NRG1/ErbB4 signal pathway regulation, suggesting that disturbed NRG1/ErbB4 signaling pathways in the Bace1-/- mouse model may contribute to the pathophysiology of schizophrenia." (PMID 28993723, 2017). "However, it has been recently demonstrated that BACE1 knockout mice exhibit a number of schizophrenia-like behavioural traits, most likely because BACE1 is involved in the cleavage of neuregulin-1, which has been linked to the pathogenesis of schizophrenia and related psychiatric disorders." (PMID 18564425, 2008). "In addition, we noted that BACE1-null mice were mostly running along the corners and spent much less time in the central space in the open-field arena when compared to WT mice (N = 12, *P < 0.05, Student’s t test), likely attributed to schizophrenia-like behaviors as suggested." (PMID 34158621, 2021). "As a transmembrane protease, BACE1 is important for several disease-related substrates, including beta amyloid peptide production in AD and NRG1 in schizophrenia." (PMID 28993723, 2017). "It is suggested that only measuring BACE1 protein levels in the brain might not be sufficient to show BACE1-specific activity in cleaving NRG1 in schizophrenia." (PMID 28993723, 2017). "However, to our knowledge, there is no study of BACE1-dependent NRG1 cleavage activity in living patients with schizophrenia." (PMID 28993723, 2017). "Additionally, the Bace1-/- mice treated with a glutamatergic psychostimulant showed impaired PPI, working memory, and social recognition, as well as spontaneous hyperactivity as schizophrenia-like behaviors." (PMID 28993723, 2017).
schizophrenia (continued). "Subsequent studies have found that BACE1 null mice have higher offspring mortality, decreased myelination, impaired memory, hyperactivity, axon mis-guidance, schizophrenia-like phenotypes, and increased seizure activity, but these phenotypes are largely absent from BACE1+/− mice." (PMID 25567526, 2015). "However BACE1 inhibition should not be complete to prevent potential side effects (hypomyelination, schizophrenia- and epileptic-like behaviors, hippocampal neurodegeneration) linked to BACE1-associated proteolysis of other substrates." (PMID 23039869, 2012). "Lack of BACE1 processing of NRG1 has been proposed to be responsible for the hyperactivity and schizophrenia endophenotypes, spine density reduction, myelination deficits in central and peripheral nervous system and deficits in formation and maturation of muscle spindles observed in BACE1 null mice." (PMID 27192432, 2016).
Obesity (22 papers, 2015 to 2025). Accumulation of substantial excess body fat. "The BACE1-overexpressing mice displayed decreased InsR levels, increased adiposity, impaired glucose disposal and heightened susceptibility to obesity compared to WT mice, under both normal chow diet (NCD) and HFD." (PMID 40507910, 2025). "This suggests that obesity induced Dicer1 downregulation decreases miR‐328, preventing BACE1 silencing and causing a decrease in BAT differentiation and thermogenesis as well as BACE1‐mediated impairments in glucose metabolism and homeostasis." (PMID 35119166, 2022). "Pathologically elevated BACE1 expression in these cells has been implicated in the development of metabolic diseases, including type 2 diabetes, obesity, and cardiovascular disease." (PMID 35119166, 2022). "Nevertheless, considering that obesity and type 2 diabetes are risk factors of “sporadic” AD, we should examine the effect of the BACE1/AP-2/clathrin complex on the pathology of sporadic AD in future studies." (PMID 26414661, 2015). "BACE1 inhibitors have been found to induce weight loss and shown therapeutic potential for obesity, which may be beneficial for the therapy of metabolic dysfunction." (PMID 40507910, 2025). "Moreover, obesity or hyperglycaemia can cause up-regulation of hepatic expression of the immature form of Bace1 that is implicated in insulin receptor shedding." (PMID 35873003, 2022). "Immune cells, including T cells and macrophages, important contributors to inflammation, hyperglycemia and obesity‐associated T2D,151 have recently been found to be abundant in BACE1 protein suggesting it might play a role in their function." (PMID 35119166, 2022). "However, the activity of BACE1 is not limited to the brain, it is identified in various cell types and implicated in a variety of physiological and pathological processes, including metabolic diseases and obesity." (PMID 39823480, 2025). "Accordingly, systemic up-regulation of human or mouse Bace1 causes endoplasmic reticulum stress and neuronal damage reflected by hypothalamic energy homeostasis circuits impairment leading to insulin resistance, hepatic deficits, and aggravation of high fat diet-induced obesity in mice." (PMID 35873003, 2022). "In addition, BACE1 has been studied in relation to insulin deficiency and obesity." (PMID 27656136, 2016). "Although BACE1 expression is highest in the brain, it is also found widely in peripheral tissues such as pancreatic β-cells, adipocytes and hepatocytes, where its elevated expression may cause metabolic disorders including DM and obesity via Aβ-independent processes." (PMID 41446639, 2025). "Previous studies have shown that Bace1 deletion or inhibition protects mice from diet-induced obesity." (PMID 37761913, 2023). "The proposed metabolic roles of BACE1 are supported by the common mechanisms and treatment targets between T2D, obesity, and AD, with the use of various antidiabetic and metabolic therapies in the treatment of AD showing promising results." (PMID 35119166, 2022). "Taken together, this suggests BACE1 is a pivotal enzyme in the development of cellular leptin resistance observed in obesity and T2D; however, the mechanism is unclear." (PMID 35119166, 2022). "These key enzymes can control the occurrence of type II diabetes (α-amylase and α-glucosidase), obesity (lipase) and AD (acetylcholinesterase (AChE), butyrylcholinesterase (BChE) and β-secretase (BACE-1))." (PMID 35684288, 2022). "In a variety of pathological conditions, including AD, cerebral amyloid angiopathy, and metabolic diseases such as type 2 diabetes and obesity, BACE1 expression and activity are increased and drive disease progression." (PMID 35119166, 2022). "Obesity induced by HFD-fed rats for 16 weeks significantly increased BACE-1 gene expression in the brain." (PMID 32397362, 2020). "We verified BACE1 expression and Aβ accumulation in the hippocampus and cortex to confirm the effect of obesity." (PMID 32555166, 2020).
Obesity (continued). "The protease Bace1 drives beta amyloid (Aβ) production with obesity elevating hypothalamic Bace1 activity and Aβ1–42 production." (PMID 29311632, 2018). "Finally, this review aims to examine the possibility that BACE1 inhibitors could provide a innovative treatment for obesity and its comorbidities." (PMID 35119166, 2022). "In addition to its neuronal roles, changes in BACE1 activity have been associated with physiological functions including maintenance of the blood–brain barrier (BBB), angiogenesis, protection against obesity, immune and antimicrobial properties, inflammatory response, and tumor suppression." (PMID 35119166, 2022). "Importantly, Bace1 is known to be up-regulated in ARH of obese mice causing a disruption of metabolic circuits of the first-order neurons resulting in insulin intolerance, aggravated high fat diet-induced obesity and other phenomena associated with metabolic syndrome." (PMID 35873003, 2022). "To understand the mechanisms through which Bace1 reduction lowers body weight and resists HFD mediated obesity, we first measured hypothalamic neuropeptide gene expression." (PMID 29311632, 2018). "Another group showed that mice lacking BACE1 are lean, resistant to diet-induced obesity and display increased peripheral tissue insulin sensitivity with improved whole-body glucose disposal." (PMID 27656136, 2016).
Insulin resistance (20 papers, 2014 to 2025). Increased resistance towards insulin, that is, diminished effectiveness of insulin in reducing blood glucose levels. "Activation of this kinase has multiple consequences, as it further deteriorates insulin resistance, promotes the transcription of BACE1, causes hyperphosphorylation of tau and inhibits the transcription factor Nrf2." (PMID 40295359, 2025). "In T2DM, chronic hyperglycemia and insulin resistance are linked to increased BACE-1 levels and activity, as insulin signaling typically regulates BACE-1." (PMID 39766390, 2024). "However, the discovery of IR as a new BACE1 substrate reveals that BACE1-inhibiting strategies may have the advantage of alleviating peripheral insulin resistance and reducing DM-associated AD risks." (PMID 41446639, 2025). "Given a growing body of research showing that increased Aβ and insulin resistance elevate BACE1 level/activity, BACE1 represents a key molecule that is situated at the crossroads of a vicious circle between AD and DM." (PMID 41446639, 2025). "Meanwhile, in HUBC mice, we noted that BACE1 overexpression led to a decreased InsR level, whose downstream pathway is important in glucose homeostasis and insulin resistance." (PMID 40507910, 2025). "sAPPβ administration mimics palmitate induced ER stress, inflammation and insulin resistance in skeletal muscle and adipose tissue, which is reduced with BACE1 inhibition." (PMID 35119166, 2022). "The action of liraglutide regarding both Aβ production and alleviating insulin resistance has been shown to occur via reducing BACE1 activity." (PMID 35119166, 2022). "We propose that increased levels of central BACE1 promotes metabolic disturbance via inducing hypothalamic impairment, ER stress, and Aβ and lipid accumulation, leading to neuronal damage, insulin resistance, hepatic deficits and global glucose dyshomeostasis." (PMID 27138913, 2016). "Studies of high fat feeding in transgenic mouse models of AD or diabetic rodent models have shown that insulin resistance can lead to an increase in the expression of key enzymes that generate Aβ (BACE1 and γ-secretase)." (PMID 26693205, 2015). "Metformin treatment of a cell model for insulin resistance has previously been reported to attenuate Aβ production, in agreement with our observation of metformin inhibiting BACE1 protein production." (PMID 25025689, 2014). "Insulin resistance causes over-activation of BACE1 in the brain, which not only causes increased production of amyloid beta plaques but also lowers the activity of insulin-degrading enzyme (IDE) to remove Aβ effectively." (PMID 41003796, 2025). "Remarkably, BACE1 level/activity is found to increase under insulin resistance in type 2 DM patients and animal models, which may represent a contributing factor to the progression to AD." (PMID 41446639, 2025). "Additionally, insulin resistance in mice—induced by a high-fat diet—results in increased activity of BACE1 and γ-secretase, contributing to the accumulation of Aβ." (PMID 40149843, 2025). "Aberrantly upregulated BACE1 degradation of functional membrane IR in the liver and increased plasma soluble IR are observed in diabetic patients as well as in db/db and HFD mouse models of type 2 DM, representing a mechanism of directly BACE1-mediated insulin resistance." (PMID 41446639, 2025). "While this review is mainly focused on BACE1, other approaches that target the mechanisms or pathways intersecting with insulin resistance and β-amyloidosis such as antidiabetic treatments are currently under preclinical and clinical investigations and have been reviewed in detail elsewhere." (PMID 41446639, 2025). "Notably, BACE1 could cleave the insulin receptor (InsR), leading to reduced InsR levels, which may impair insulin signaling and contribute to insulin resistance." (PMID 40507910, 2025).
Insulin resistance (continued). "Moreover, BACE1 elevation occurs through the downregulation of microRNA (miR-6838-5p) in the adipose tissue of HFD-fed mice, while BACE1 suppression via miR-6838-5p overexpression can reverse insulin resistance and increases in blood glucose and body weight to normal levels." (PMID 41446639, 2025). "Insulin resistance, as highlighted in earlier sections, reduces amyloid-beta clearance due to IDE competition and enhances its production through BACE1 activation." (PMID 41003796, 2025). "It has been found that insulin resistance increased APP metabolism and BACE-1 expression." (PMID 40076550, 2025).